FAP (fibroblast activation protein alpha)
Diseases named in the same sentence as FAP in open-access papers (continued):
Sharing a sentence is not in itself a finding about the gene and the disease.
breast carcinoma (continued). "FAP expression was significantly up-regulated in pancreatic and breast cancer, indicating that FAP-positive cells were abundant in these two cancers." (PMID 37046312, 2023). "In this study, we observed a unique hybrid population expressing pan-CK and the mesenchymal cell marker FAP in clinical tissue samples of primary invasive carcinomas and distant breast cancer metastasis that have failed chemotherapy." (PMID 37607007, 2023). "FAP-α and a catalytically inactive mutant of FAP-α in human breast cancer cells increased tumor growth in vivo and invasiveness in culture." (PMID 36937451, 2023). "Although primarily expressed by CAFs, FAP-α expression has also been detected in breast cancer, astrocytoma, melanoma, colorectal cancer, and oral squamous cell carcinoma cells." (PMID 36937451, 2023). "Our studies have identified new functional roles of FAP-α that expand our understanding of this important target in triple negative MDA-MB-231 human breast cancer cells." (PMID 36937451, 2023). "The intensity of FAPI imaging agent uptake by various tumors is closely related to the degree of FAP expression, e.g., breast cancer and esophageal cancer, where FAP expression levels are high and tumor uptake of FAPI imaging agent is very high (SUVmax >12)." (PMID 35692767, 2022). "There is no doubt that the feasibility of [68Ga]Ga-FAPI will promote more theranostic approaches to FAP-targeted radiotherapy for breast cancer in the future." (PMID 35565232, 2022). "[99mTc]Tc-iFAP uptake was considerably lower regarding [18F]FDG in patients with cervical cancer and neuroendocrine tumor (NET) of the adrenal cortex, which agrees with their relatively low FAP expression in comparison to lung and breast cancer." (PMID 35745648, 2022). "The highest FAP immunohistochemistry scores were observed in pancreatic, esophageal, and breast cancer." (PMID 34740953, 2022). "The abundance of CAFs, especially the FAP+ subset, has been clinically related to a poor prognosis in a number of cancers, including lung cancer, breast cancer, and CRC." (PMID 36275750, 2022). "α-SMA had been reported in the previous literature to be highly expressed in TNBC and luminal A breast cancer, but FAP expression in some kinds of breast cancer is low, so α-SMA as maker for CAFs is feasible." (PMID 36382024, 2022). "We also found that in MMTV-PyMT mammary tumor specimens integrin α11 is strongly associated in breast cancer specimens with a PDGFRβ+ CAF subset and to lower degrees with PDGFRα, α-SMA, NG2 and FAP." (PMID 35378690, 2022). "Immunofluorescence staining and immunohistochemical staining were used to further verify the higher expression of α-SMA and FAP in CAFs or breast cancer tissues." (PMID 34853307, 2021). "Analyses of histopathology suggested that strong-to-moderate FAP expression is present in the stroma of breast carcinomas." (PMID 34050777, 2021). "According to the literature, deletion of HIF‐1α in FAP positive fibroblasts accelerates the growth of breast cancer in transgenic mice." (PMID 33943003, 2021). "The current imaging findings are partially in concordance with previous histopathology studies, which presented intermediate expression of FAP in endometrial cancer, cervix cancer, and ovarian cancer and high expression in breast cancer." (PMID 34050777, 2021). "In patients with breast cancer, the lesions presented a moderate uptake in relation to a rather high expression of FAP." (PMID 34050777, 2021). "A large number of studies have confirmed that FAP is expressed on the microvascular endothelial cells of malignant tumor tissues, such as multiple myeloma, gastric cancer, and breast cancer." (PMID 34490078, 2021). "CAF markers that have been associated with promotion of breast cancer tumor growth through several experiments include α-SMA, FAP, PDGFR-α, PDGFR-β, CD29, neural/glial antigen 2 (NG2), FSP1, vimentin, and podoplanin (PDPN)." (PMID 33808627, 2021).
breast carcinoma (continued). "As 61% of BCAFs generated from primary culture of murine breast cancer and less than 1% of cancerous cells displayed FAP expression in this study, HNav-FAP induced cytotoxicity in BCAFs, not cancerous cells." (PMID 34944738, 2021). "Within our exemplary staining of a pleural biopsy in a patient diagnosed with breast cancer, very high FAP expression in the stroma and strong-to-moderate expression in the neoplastic cells and tumor cell nests were observed as well." (PMID 34050777, 2021). "Here, we report the engineering and testing of BiMAb and bifunctional TNFL fusion proteins targeting various well-established breast cancer-associated TAAs, including EGFR, HER2, CEA, EpCAM, and the tumor stroma antigen FAP." (PMID 34484225, 2021). "Comparison of tumors from NeuT/ATTAC+AP mice with biopsies of HER2+ breast cancer for fibrosis markers indicated several commonalities, including FAP (fibroblast activation protein), Ccl5, S100aA9 and collagen expression." (PMID 33780491, 2021). "A mouse breast cancer model revealed that epirubicin conjugated with a FAP-specific dipeptide (Z-Gly-Pro) effectively releases epirubicin after incubation with FAP, and epirubicin induces a substantial anti-tumor effect in cells with high FAP expression (4T1)." (PMID 34490078, 2021). "The third specimen, which was performed on a pleural metastasis due to breast cancer, depicted strong FAP expression within the stroma and strong-to-moderate FAP staining of the neoplastic cells." (PMID 34050777, 2021). "FAP overexpression has been identified in breast cancer, in particular in the stroma but also in the cancer cells themselves." (PMID 34638433, 2021). "For 4T1 breast cancer models, 4T1 tumor tissue showed FAP expressing and high uptake was seen in FAP-expressing 4T1 tumor and bladder (4T1 tumor SUVmax 5.7)." (PMID 33816303, 2021). "Their findings are consistent with past studies in which FAP expression was discovered on macrophages in human breast cancer." (PMID 34068501, 2021). "In effect the Bi-FAP/mEnd-IL based fluorescence was localized only in the tumor vasculature and myofibroblasts of the breast carcinoma model." (PMID 32316521, 2020). "In breast cancer, a FAP-positive CAF subpopulation promoted an immune-suppressive environment by enhancing the regulatory T-cell capacity to inhibit T-effector proliferation." (PMID 33153037, 2020). "In breast cancer, CAFs positive for both FAP and podoplanin are immunosuppressive through a nitric oxide (NO)-dependent mechanism." (PMID 32546182, 2020). "Breast cancer cell stemness was also maintained by exosomes containing miR-221, which was abundantly released by vimentin-expressing FAP+ fibroblasts in bone marrow." (PMID 33050237, 2020). "Preliminary support is available from demonstrations that FAP-positive S1 breast cancer fibroblasts promote the formation of FoxP3-positive T cells in a manner involving B7H3, CD73 and DPP4." (PMID 33153037, 2020). "We validated this concept in xenografted mice models based on human fibrosarcoma cells that stably expressed high levels of human FAP protein, and also a human breast carcinoma model that lack FAP expression." (PMID 32316521, 2020). "The MDA-MB231 xenograft composed of a human breast cancer cell line which lack FAP and murine endoglin expression in vitro." (PMID 32316521, 2020). "Of note, FAP expression has also been documented on pericytes in breast cancer, and FAP has been investigated as a target for pericyte‐directed vascular disrupting agent (VDA) therapy in several tumor models." (PMID 33082953, 2020). "Tumor digests were implanted (5x105 cells/injection) into the mammary fat pads of WT and FAP KO mice given that FAP expression is elevated in human breast cancer." (PMID 30726287, 2019). "CC-chemokine ligand 5 (CCL5) production by FAP+α-SMA+ CAFs in mammary carcinoma has appeared to preferentially recruit Tregs, owing to the highly expressed CC-chemokine receptor 1 (CCR1) by Tregs." (PMID 31462327, 2019).
breast carcinoma (continued). "Whereas HER2 is the therapeutic target in the case of breast cancer, the role of FAP in immunotherapy is not well understood." (PMID 31337426, 2019). "In the present study, we have demonstrated that FAP+ HO-1+ TAMs found in the microenvironment of human and murine breast cancers represent an innate wound healing response phenotype." (PMID 30054470, 2018). "To gain a further insight of the role of CAFs in the clinical setting, we collected 59 breast carcinoma samples and examined markers of CAFs FAP-α and α-SMA by immunohistochemistry." (PMID 29325547, 2018). "FAP is known to be overexpressed in CAS from human breast cancer as well, and has the capacity to degrade gelatin and type 1 collagen and therefore influences the remodelling of the ECM, supporting the formation of a tumour-permissive milieu." (PMID 28531107, 2017). "Taken together, our results showed that at least COL1A1, ACTA2, and FAP were significantly upregulated on mRNA levels in CAS from canine mammary carcinoma similar to human mammary carcinoma samples, whereas CXCL12 is downregulated." (PMID 28531107, 2017). "Furthermore, the recent observation that FAP positive cancer associated fibroblasts are present in the peripheral blood of metastatic breast cancer patients may throw interesting light upon the ability of synovial fibroblasts to spread to distant sites in mouse models of arthritis." (PMID 28793332, 2017). "Here, we found that exogenous TNF-α enhances the accumulation of both MT1-MMP and CD26 and, additionally, FAP-α in lipid rafts in different breast cancer-derived cells." (PMID 27042827, 2016). "It was further shown that FAP-targeted elimination of TAFs in the 4T1 mouse model of breast cancer reduced infiltration of TAMs and other immune cells to the tumor site." (PMID 26934296, 2016). "Another study using shRNA to target FAP α in a mouse model carrying 4T1 breast cancer came to the same conclusions." (PMID 26985769, 2016). "Previous studies have shown that a DNA vaccine targeting FAP induced a shift in local immunity from Th2 to Th1, which favors the destruction of malignant cells, in a murine breast cancer model." (PMID 26394925, 2015). "In conclusion, we report that FAP-α expression in patients with breast cancer is increased with poor prognosis and patient survival." (PMID 24885257, 2014). "In vitro results showed that breast cancer cells over expressing FAP-α had increased growth ability and impaired migratory ability." (PMID 24885257, 2014). "The human breast cancer cell line BT549 was used as a positive control for endogenous FAP-α expression." (PMID 24885257, 2014). "The human breast cancer cell line MDA-MB-231 expressing FAP-α grew more rapidly and was produced highly vascular tumours in vivo." (PMID 24885257, 2014). "Breast cancer cells expressing a catalytically inactive mutant of FAP-α (FAPS624A) also produced tumours that grew rapidly." (PMID 24885257, 2014). "Our data has shown that in patients with breast cancer, FAP-α is significantly over-expressed in those with poor prognosis and is inversely related to both overall and disease-free survival." (PMID 24885257, 2014). "In vitro, FAP-α promotes proliferation and inhibits migration of breast cancer cells, potentially by regulating the FAK pathway." (PMID 24885257, 2014). "We also suggested the possibility of FAP-α promoting the formation of microemboli, which facilitate the metastasis of breast cancer." (PMID 22067528, 2011). "Here we also performed assays using the same breast cancer lines on our FAP+ matrices and found that FAP+ matrices effectively recapitulate many aspects of tumor-associated ECMs." (PMID 21668992, 2011). "We suggested the possibility of FAP-α promoting the formation of microemboli that facilitates the metastasis of breast cancer." (PMID 22067528, 2011).
breast carcinoma (continued). "In summary, FAP+ 3D matrices represent a permissive environment for pancreatic (and breast cancer) invasion, and perhaps these matrices play an equally important role along with the epithelial cell component." (PMID 21668992, 2011). "FAP (seprase) is a membrane-bound protease that has been suggested to reduce the dependence of breast cancer cells on exogenous growth factors in vitro and thereby to facilitate tumour growth and metastasis." (PMID 17069663, 2006). "Similarly, in breast cancer, FAP‐positive (FAP+) CAFs demonstrated peritumoral and perivascular localization, with dipeptidyl peptidase 4 (DPP4)/YAP1‐driven plasticity linking their distribution to immune exclusion and invasion." (PMID 40656546, 2025). "For CAFs, FAP is a therapeutic target in the TME of breast cancer that is HER2-positive." (PMID 39755633, 2025). "This may open opportunity for emerging FAP based radioligand for therapeutic applications in advanced stage breast cancers." (PMID 39744055, 2025). "Competition and internalization studies on FAP-expressing cells reveal a FAP specificity in the nanomolar range and a high internalization rate, which was propaedeutic to the preclinical validation of the tracer on a breast cancer murine model." (PMID 40762892, 2025). "Certain FAP+ CAF clusters have been correlated with the invasive properties of breast cancer, suggesting that the heterogeneity among FAP+ CAFs may play a pivotal role in the progression of DCIS." (PMID 39439806, 2024). "Here, we analyze trajectory inference, deconvolute spatial transcriptomics at single-cell level and perform functional assays to generate a high-resolution integrated map of breast cancer (BC), with a focus on inflammatory and myofibroblastic (iCAF/myCAF) FAP+ CAF clusters." (PMID 38561380, 2024). "Previous studies have identified four subsets of CAFs in breast cancer (CAF-S1 to CAF-S4); CAF-S1 was associated with an immunosuppressive TME and preferentially detected in TNBC, it is also the only subset of CAF with increased FAP expression." (PMID 38587644, 2024). "In breast cancer, eight clusters were identified in the FAP+/CAF‐S1 population." (PMID 36772945, 2023). "In addition, the studies show that CAF-S1 subtype, which have high Alpha SMA and FAP positivity have clearly demonstrated an immunosuppressive function in breast cancer and attract FOXP3 regulatory T-cells." (PMID 38192631, 2023). "In addition, FAP expressed by CAFs is an independent factor predicting the prognosis of breast cancer patients, and the expression of FAP is correlated with cancer cell metastasis and survival." (PMID 37496657, 2023). "In other words, autophagy and FAP are required for breast cancer cell invasion and metastasis." (PMID 37316886, 2023). "FAP-α is also expressed by some cancer cells, such as melanoma, colorectal and breast cancer cells." (PMID 36937451, 2023). "While FAP-a-expressing active fibroblasts promote breast tumorigenesis and are implicated in an immunosuppressive environment, CD10+ GPR77+ as well as CD44+ active breast fibroblasts promote breast cancer stemness and chemoresistance." (PMID 36359766, 2022). "Consequently, in vivo elimination of CAFs in a murine model of breast cancer using a vaccine targeting FAP can shift CD4+ T cell polarization from a Th2 to a Th1, increase expression of IL-2, increase CD8+ T cell functions, and hamper Tregs recruitment." (PMID 36338519, 2022). "In breast cancer, fibroblast activation protein- (FAP-) positive CAF could suppress immune by enhancing the regulatory T cells and inhibiting T cell effectors." (PMID 35505821, 2022). "However, several studies have demonstrated that FAPα is also expressed in certain cancer cells, including colorectal cancer, pancreas cancer, stomach cancer and breast cancer 67-70." (PMID 34976180, 2022).
breast carcinoma (continued). "Another study of fibroblasts that were transfected with enzymatically inactive FAP revealed increased growth and migration of breast cancer cell lines, with FAP activating the phosphoinositide 3-kinases (PI3Ks), matrix metallopeptidase 2, and matrix metallopeptidase 9 signaling pathways." (PMID 34490078, 2021). "Effective co-stimulation could be achieved by targeting a second breast cancer antigen, or by targeting fibroblast activation protein (FAP) expressed on another target cell." (PMID 34484225, 2021). "In human breast cancer, isolation of a FAP+PDGFRβ+ CAF subset was shown to promote survival and differentiation of inhibitory Tregs via both a cell contact and paracrine mechanism involving CXCL1245 and was extended to mesenchymal high-grade serous ovarian cancers." (PMID 34740105, 2021). "Furthermore, immunohistochemistry staining demonstrated a strong FAP expression in ovarian cancer, breast cancer and leiomyosarcoma of the uterus, which is in concordance with previous studies." (PMID 34638433, 2021). "However, in both our models we observe increased numbers of FAPα+ CAFs but significant less PDPN+ CAFs as the tumours developed, underlining the difficulty in dissecting the biological function of FAPα+PDPN+ CAFs in breast cancer." (PMID 34016130, 2021). "Similarly, breast cancer cell lines were transfected with a version of FAP that had low enzymatic activity exhibited faster tumor growth in vivo and faster degradation of the extracellular matrix (vs. untransfected cell lines)." (PMID 34490078, 2021). "Besides the stable human FAP and murine endoglin expressing cells, the breast cancer cell line MDA-MB231 and the wild type of the fibrosarcoma cell line, HT1080, which lack expression of the FAP and murine endoglin proteins were also implemented." (PMID 32316521, 2020). "Thus, FAP-a was potentiated in the promotion of the formation of microemboli, which promotes the invasion of breast cancer." (PMID 31921678, 2019). "We further hypothesized the participation of FAP-a in designating the microemboli's formation, facilitating the pathological process of breast cancer." (PMID 31921678, 2019). "Here we report, using murine models of breast cancer, that TAMs expressing fibroblast activation protein alpha (FAP) and haem oxygenase-1 (HO-1), which are also found in human breast cancer, represent a macrophage phenotype similar to that observed during the wound healing response." (PMID 30054470, 2018). "Overexpression of FAP is associated with poor outcome in some neoplasm (pancreatic, hepatocellular, and colonic malignancies) but not others (breast cancer)." (PMID 27936466, 2017). "Besides, FAP-activated prodrugs have been tested in prostate and breast cancer with promising results." (PMID 28033421, 2016). "Eliminating CAFs in a 4T1 murine breast cancer model of metastatic breast cancer by injecting a DNA vaccine targeting FAP led to decreased expression of pro-angiogenic factors, such as VEGF, PDGFR and GM-CSF, and resulted in suppression of angiogenesis and lymphangiogenesis." (PMID 26828520, 2016). "In searching for the potential pathway(s) that may be responsible for the impact of FAP-α expression on breast cancer cells, we screened a panel of small molecule inhibitors to some of the key signalling pathways that are linked to cell motility." (PMID 24885257, 2014). "The purpose of this work was to investigate the role of FAP-α in human breast cancer." (PMID 24885257, 2014). "For example, circulating CAFs can be detected in the blood of both breast cancer and prostate cancer with high levels of CAFs, and circulating CAFs exist in 88% of metastatic breast cancer patients and 23% of non metastatic patients (based on the expression of FAP and actin alpha 2 ACTA2)." (PMID 37666813, 2023).